PROX1 (prospero homeobox 1)
Diseases named in the same sentence as PROX1 in open-access papers (continued):
Sharing a sentence is not in itself a finding about the gene and the disease.
glioblastoma (9 papers, 2016 to 2026). The most malignant astrocytic tumor (WHO grade IV). "This study verified that TPL inhibited the progression of glioblastoma cells by transcriptionally depressing the expression of PROX1." (PMID 36969058, 2023). "Taken together, the present study verified that TPL has a tumor-suppressive effect against glioblastoma cells by depressing PROX1 expression." (PMID 36969058, 2023). "PROX1 overexpression enhanced the proliferation of glioblastoma cells and promoted the growth of glioblastoma xenograft tumors, and this invasiveness potential was regulated via activation of the NF-κB signaling pathway." (PMID 32370142, 2020). "From this point of view, PROX1 can be used as a target of glioblastoma." (PMID 36969058, 2023). "Moreover, ectopic expression of PROX1 partially rescued the effects of TPL on glioblastoma cell viability, proliferation, apoptosis, migration and invasion, and on the expression of cell function-related genes." (PMID 36969058, 2023). "Moreover, over-expression of PROX1 distinctly reversed the TPL- induced inhibition of glioblastoma cell growth, migration, and invasion, as well as enhancement of apoptosis." (PMID 36969058, 2023). "Furthermore, it has been reported that high levels of the human homologue of Pros, PROX1, exacerbate glioblastoma, arguing against PROX1 expression as a therapeutic strategy." (PMID 32073402, 2020). "However, other reports have demonstrated that the upregulation of PROX1 is a predictor of poor outcomes in colon cancer, glioblastoma, and vascular endothelial tumors." (PMID 31717665, 2019). "We hypothesized that PROX1 is a prognostic factor for patients with primary glioblastomas, the most common type of glioblastoma that arises in older patients and lacks IDH1/2 mutations." (PMID 27626492, 2016). "In this study, we further validated the anti-tumor effects of TPL and explored the role of PROX1 on TPL-induced inhibition of cell proliferation, migration and invasion, and enhancement of apoptosis using the human glioblastoma U251 cell line." (PMID 36969058, 2023). "In contrast, high expression of PROX1 protein predicted shorter survival in the group of patients with IDH-mutant anaplastic astrocytomas and secondary glioblastomas." (PMID 27626492, 2016). "Accompanying with the expression of PROX1, the effect of TPL on glioblastoma cell viability, proliferation, apoptosis, migration and invasion was partially attenuated, and on the expression of cell cycle, apoptosis and invasion–related genes were also weakened." (PMID 36969058, 2023). "In three consecutive steps, we showed that PROX1 protein levels correlated with survival for patients with IDH-mutant high-grade astrocytomas but not for patients with primary glioblastomas." (PMID 27626492, 2016). "The present study does not provide evidence for PROX1 as an age-dependent prognostic marker in primary glioblastomas." (PMID 27626492, 2016). "Due to the low number of IDH-mutant glioblastomas in our TMAs and in TCGA, we were not able to compare survival by PROX1 expression for patients with secondary glioblastomas separately." (PMID 27626492, 2016). "The negative results for PROX1 in the group of primary glioblastomas may therefore also exemplify the general difficulties to identify new biomarkers for patients with such a short survival time." (PMID 27626492, 2016). "The prognostic impact of PROX1 in IDH-mutant 1p19q non-codeleted high-grade astrocytomas, as well as the negative findings in primary glioblastomas, was corroborated by gene expression data extracted from the Cancer Genome Atlas." (PMID 27626492, 2016). "For studying PROX1 gene expression in correlation to survival, we extracted IDH-mutant 1p19q non-codeleted anaplastic astrocytomas and glioblastomas from TCGA." (PMID 27626492, 2016). "Finally, both TPL and PROX1 were reported to affect NF−κB activation, there is a lack of detection of NF−κB activation by PROX1 and TPL in glioblastoma cells." (PMID 36969058, 2023).
neuroblastoma (8 papers, 2014 to 2025). Neuroblastoma (NB) is the most common solid, extracranial childhood tumor. "PROX1 aids in the growth and lymphatic dissemination of neuroblastomas, and there is a correlation between tumor lymphatic density and lymph node metastases." (PMID 40660330, 2025). "Nevertheless, we previously reported that Prox1 promotes the expression of the CDKN1B gene (encoding for p27-KIP1) in mouse and human neuroblastoma cells." (PMID 37508533, 2023). "We also reported that Prox1 suppresses cell cycle progression and proliferation of neuroblastoma cancer cells via a direct action in basic components of the cell cycle machinery." (PMID 25674048, 2014). "Accordingly, we have recently unraveled the key role of Prox1 in regulating the fine balance between proliferation and differentiation of NSCs during spinal cord development and neuroblastoma cancer progression." (PMID 25674048, 2014). "Additionally, it was also demonstrated that PROX1 strongly inhibits the proliferation of neuroblastoma cell lines as well as cyclin D1, cyclin-A, and cyclin B1, consistent with a role in cell cycle arrest." (PMID 25526434, 2014).
esophageal cancer (7 papers, 2014 to 2022). A primary or metastatic malignant neoplasm involving the esophagus. "In more detail, PROX1’s high expression is associated with worse prognoses and shorter OS in cases of CNS tumors, colon, gastric, and esophageal cancer." (PMID 35885529, 2022). "In this context, the A-to-G mutation affects PROX1 function in human specimens of pancreatic, colon, and esophageal cancers and A to I in esophageal cancer." (PMID 32370142, 2020). "For instance, high Prox1 expression in human colon and esophageal cancer tissues is correlated with poor prognosis." (PMID 34183992, 2021). "Prox1 mediates the antiproliferative impact of IFN-γ in esophageal cancer cells and Prox1 might be a viable target for new esophageal cancer treatment methods." (PMID 35346069, 2022). "A statistically significant relationship was found between all three lymphoendothelial markers when measured in surgical samples of esophageal carcinoma; LYVE with PROX1 and VEGFR-3, and VEGFR-3 with PROX1." (PMID 35885529, 2022).
lung carcinoma (7 papers, 2010 to 2025). "Finally, genetic ablation of PROX1 renders LKB1‐deficient KRAS-driven lung cancer resistant to phenformin treatment." (PMID 36433955, 2022). "Further mechanistic and immunologic studies are warranted to elucidate the functional significance of PROX1 in lung cancer biology." (PMID 40843762, 2025). "The expression of ASCL1, FOXA2, and PROX1 positively correlated in prostate cancer patient datasets as well as lung cancer." (PMID 39470735, 2024). "Despite the strong proof of concept, the study needs to further investigate the role of Prox1 in the proliferation, migration, and invasion of lung cancer cells, and the role between Rho protein and Cyclin D1 need to be further demonstrated." (PMID 34183992, 2021). "In the current study, we transfected plasmid overexpressing Prox1 and plasmid siRNA silencing Prox1 to study the role of Prox1 in the proliferation, invasion, and migration of A549 and H446 lung cancer cells." (PMID 34183992, 2021). "The current study investigates the effect of transcription factor Prox1 on the proliferation, migration, and invasion ability of lung cancer." (PMID 34183992, 2021). "So, the expression of Prox1 was related to the proliferation, migration, and invasion of lung cancer cells." (PMID 34183992, 2021). "Relevant studies show that Prox1 expression is related to tumor stage and grade, suggesting that Prox1 participates in the proliferation process of lung cancer cells." (PMID 34183992, 2021). "Prior to investigate the effect of Prox1 on the migration and invasion of lung cancer cells, we firstly confirmed the expression of Prox1 in A549 and H446 cells overexpressing Prox1 after plasmid transfection." (PMID 34183992, 2021). "Moreover, the overall survival times and disease-free survival appeared to be shorter in lung cancer patients with higher PROX1 and were prolonged in cases of higher Ser79 phosphorylation." (PMID 36433955, 2022). "Studies investigating the role of PROX1 in lung cancer pathogenesis are relatively sparse." (PMID 35885529, 2022). "Moreover, the role of Prox1 also need to be examined in an appropriate lung cancer animal model to get a more in-depth insight." (PMID 34183992, 2021). "Therefore, western blot and real-time PCR analyses were used to detect the expression of RhoA, RhoB, and RhoC in A549, H446 lung cancer cells transfected with plasmid Prox1 and interfering siRNA." (PMID 34183992, 2021). "The experimental results suggested that the increased expression of Prox1 could promote the growth of lung cancer cells." (PMID 34183992, 2021). "In this study, lung cancer A549 and H446 cells were transfected with Prox1NAD and siRNA plasmids, respectively, so that cells transfected with Prox1NAD plasmids overexpressed Prox1 and cells transfected with siRNA had low expression of Prox1." (PMID 34183992, 2021). "Similarly to PROX1, both SOX18 and COUP-TFII are associated with regulation in malignancy of various cancer types, such as gastric, breast, and lung cancers, and they are connected with vascularization of tumors." (PMID 32370142, 2020). "In our Lab small lung cancer cells have been detected Prox1 200 fold higher than control cells." (PMID 23675176, 2010). "Therefore, Prox1 can regulate the proliferation of lung cancer cells by binding to Cyclin D1." (PMID 34183992, 2021). "The results suggested that the expression of Prox1 could promote the growth of lung cancer cells." (PMID 34183992, 2021). "Here, the authors show that AMPK activation decreases Prospero-related homeobox 1 (PROX1) levels impairing branched amino acid metabolism and tumourigenesis in liver and lung cancer models." (PMID 36433955, 2022).
lung carcinoma (continued). "Considering that the high expression of PROX1 imposes selective vulnerability via BCAAs, dietary BCAA limitation may be a potential intervention for treating HCC and lung cancer patients with aberrant PROX1 expression." (PMID 36433955, 2022). "Thus, our study clearly illustrates that Ser79 nonphosphorylated PROX1 is an oncogenic driver in tumourigenesis and aggressiveness, at least in HCC and lung cancers." (PMID 36433955, 2022).
prostate carcinoma (7 papers, 2022 to 2026). A carcinoma that arises from epithelial cells of the prostate gland. "Identifying PROX1 upregulation in tumors may help to stratify patients at greatest risk of eventually developing more terminally differentiated forms of prostate cancer such as DNPC or NEPC." (PMID 40454483, 2025). "In summary, our work suggests that PROX1 is a factor activated early in lineage plasticity and a target of interest across the prostate cancer lineage plasticity continuum worthy of further study." (PMID 40454483, 2025). "We sought to determine the PROX1 expression pattern in representative prostate cancer models, including those recapitulating the spectrum of lineage plasticity." (PMID 40454483, 2025). "PROX1 expression positively correlated with neuroendocrine score and negatively correlated with AR score in prostate cancer patient data sets." (PMID 39470735, 2024). "Importantly, these tumors also underwent RNA-Seq, enabling us to examine PROX1 expression in specific prostate cancer subtypes defined by the Labrecque lineage plasticity subtype classifier." (PMID 40454483, 2025). "Given the established role of lineage plasticity in the progression of prostate cancer and the loss of AR signaling pathway during NEPC development, we hypothesized that PROX1 plays a key role even prior to NEPC differentiation change." (PMID 40454483, 2025). "Additionally, PROX1 plays a key role in neuroendocrine plasticity in prostate cancer, promoting liver metastasis." (PMID 40843762, 2025). "Interestingly, Prox1, a gene expressed by progenitor cells and EECs in the normal intestine and related to neuroendocrine plasticity in prostate cancer, was identified as a marker gene of all pre-EEC and EEC clusters." (PMID 40264166, 2025). "Furthermore, our results suggest that PROX1 targeting through HDACis is a rational approach to treat tumors across the prostate cancer lineage plasticity continuum that have upregulated PROX1 and lost AR reliance." (PMID 40454483, 2025). "PROX1 is upregulated in prostate cancers undergoing lineage plasticity (differentiation change)." (PMID 40454483, 2025). "Our previous study also confirmed that DAB2IP could promote EMT and metastasis in prostate cancer by inhibiting proteasome degradation of HIF1α through targeting PROX1 transcription." (PMID 35342346, 2022). "However, there was limited information on PROX1 expression and its role in prostate cancer." (PMID 40454483, 2025).
thyroid cancer (7 papers, 2017 to 2022). "In thyroid cancer, PROX1 is downregulated; this is linked to more aggressive tumor behavior and tumor progression." (PMID 35885529, 2022). "The interdependence between PROX1 and FGF2 was linked to thyroid cancer progression and correlated with the cancer stage and OS." (PMID 35885529, 2022). "There is evidence that PROX1 is consistently downregulated by more than 2-fold in various thyroid cancers, compared to normal tissues." (PMID 35885529, 2022). "In summary, our observations demonstrated that the silencing of PROX1 expression strongly activates angiogenic markers in thyroid cancer cells, which reveals that PROX1 is involved in both processes: lymph- and angiogenesis." (PMID 31717665, 2019). "In conclusion, the present study demonstrates that PROX1 is engaged in dissemination of aggressive thyroid cancer types involving the angiogenesis pathway." (PMID 31717665, 2019). "Here, we analyzed focal adhesions (FAs) of CGTH-W-1 and FTC-133 thyroid cancer cells after PROX1 silencing in comparison to control cells treated with siNEG." (PMID 31717665, 2019). "Our findings indicate an association between pro-angiogenic factors and distant metastasis of thyroid cancer cells, which can be regulated by changes in PROX1 expression level." (PMID 31717665, 2019). "FTC is a relatively rare form of thyroid cancer, so we analyzed results of PROX1 and FGF2 expression in the PTC subtype available through the GEPIA database (Gene Expression Profiling Interactive Analysis)." (PMID 31717665, 2019). "Although decrease of PROX 1 expression in various thyroid cancers tissues was presented, there was a significant variability in the PROX1 expression in FTC cases." (PMID 31060342, 2019). "In the present study, we aimed to evaluate the potential involvement of PROX1 in the regulation of thyroid cancer angiogenesis." (PMID 31717665, 2019). "In summary, our data revealed that PROX1 is involved in the spreading of thyroid cancer cells by regulation of angiogenesis." (PMID 31717665, 2019). "In that study, reintroduction of nuclear PROX1 into a PTC cell line BCPAP suppressed the invasive phenotype of the cells implying that PROX1 inactivation contributes to thyroid carcinoma invasiveness." (PMID 29934628, 2018). "In order to determine the biological significance of Prox1 expression for malignant thyroid cancer cells, we analyzed possible interactions of the Prox1 expression with the PI3K/Akt signaling pathway." (PMID 29371975, 2017). "In this study, we have analyzed Prox1 expression in normal and malignant human thyroid carcinoma cell lines." (PMID 29371975, 2017). "Whether PROX1, among other vascular factors, enhances thyroid cancer dissemination through the regulation of angiogenesis was the subject of another study." (PMID 35885529, 2022). "Additionally, notch-induced PROX1 inactivation significantly promoted the malignant phenotype of thyroid cancer cells." (PMID 32370142, 2020). "Therefore, the provided data can be a base for the perspective research focused on thyroid cancer and the PROX1." (PMID 32370142, 2020). "Taken together, these data suggest that PROX1 expression could be regulated by DNA methylation status in thyroid cancer tissues and thyroid normal and cancer cells." (PMID 32370142, 2020). "In our previous experimental studies, we showed that PROX1 is present in the thyroid cancer (THC) cells of different origins and has a high impact on follicular thyroid cancer (FTC) phenotypes, regulating migration, invasion, focal adhesion, cytoskeleton reorganization, and angiogenesis." (PMID 32370142, 2020). "In order to gain more insight into the exact role of PROX1 in the biology of thyroid cancer cells, we have knocked down PROX1 expression in this cell line and studied the effect of this silencing on malignant characteristics of the cells, such as migration, invasion, proliferation and survival." (PMID 31060342, 2019).